TNF (tumor necrosis factor)
Diseases named in the same sentence as TNF in open-access papers (continued):
Sharing a sentence is not in itself a finding about the gene and the disease.
tumor (continued). "Through spatial and molecular profiling, they found that CD8+ cytotoxic T cells in tumor-rich regions expressed effector molecules such as PRF1, GZMK, and TNF, indicating preserved cytotoxic function." (PMID 41001043, 2025). "Its primary mechanisms of action include the inhibition of tumor cell proliferation, the enhancement of host immune responses, and the modulation of cytokines such as VEGF and TNF-α." (PMID 41221261, 2025). "Compared to those cultured with tumor cells from the control group, T cells cocultured with tumor cells from the SIRT1‐OE group exhibited reduced IFN‐γ and TNF‐α production, decreased Ki‐67 expression, and increased PD‐1 expression." (PMID 39783838, 2025). "α-MMC activates the Caspase cascade through mitochondrial pathway, and co-mediates the TNF signaling pathway through NF-κB and MAPK signaling pathways, thereby activating downstream effector factors of Caspase and inducing apoptosis of tumor cells." (PMID 40552155, 2025). "Levels of cytotoxic proteins, including STAT1, TNF-α, GZMB, and Perforin in tumor tissues were sharply enhanced by sh-TBX21 injection." (PMID 41573646, 2025). "Emodin effectively reduced PD-L1 levels in H22 cells and increased anti-tumor activity in an H22 subcutaneous tumor model by promoting CD8+ T cells infiltration and TNF-α, IFN-γ, and granzyme B secretion." (PMID 40804393, 2025). "The expressions of IFN‐γ, TNF‐α, and GzmB were significantly increased, while PD‐1 was dramatically decreased in CD8+ T cells from tumor tissues of BMDMsPRDX1‐KO group compared to the BMDMsWT group." (PMID 41306557, 2025). "High CD8+ CTL infiltration correlates with improved survival, as these cells induce tumor cell apoptosis via MHC I-dependent perforin, granzyme, TNF, and IFN-γ release, though IL-18 receptor signaling impedes their migration." (PMID 40443678, 2025). "At the same time, these cells enhance the activation of antigen-presenting cells and CD8+T cells in the liver by secreting cytokines such as interferon-γ (IFN-γ) and tumor necrosis factor-α (TNF-α), thus forming a broader anti-tumor immune response." (PMID 40141420, 2025). "Key cytokines such as interleukin-6 (IL-6), tumor necrosis factor-alpha (TNF-α), interleukin-1 beta (IL-1β), and interferon-gamma (IFN-γ) are critical mediators of tumor progression, immune tolerance, and therapy resistance." (PMID 41401147, 2025). "Treatment with the NO-donor NCX-4016 or PNT resulted in the inhibition of CAR T cell expansion and diminished ability of CAR T cells to kill tumor cells and secrete effector cytokines IFN-g and TNF-a." (PMID 40235478, 2025). "Biochemical analysis of mouse blood samples showed that the levels of tumor marker CEA and inflammatory factor TNF-α were increased in the microbial treatment group (p < 0.01), while IL-10 (an anti-inflammatory factor) was decreased (p < 0.01)." (PMID 41562055, 2025). "And for cell culture cytokine measurements, found that the SAA signaling significantly influenced the releasing of many T cell maturation/polarization and anti-tumor immunity related cytokines including, IL-1β, IFN-γ, TNF-α, IL-6 etc.." (PMID 41488634, 2025). "Inflammatory cytokines, such as IL-2, enhance the secretion of TNF-α and IFN-γ by NK cells but downregulate the tumor-suppressive lncRNA GAS5." (PMID 41229433, 2025). "It secretes a range of growth hormones, cytokines, and chemokines that support the survival and multiplication of tumor cells, including VEGF, prostaglandin E2 (PGE2), CCL17, IL-6, TNF-α, and epidermal growth factor (EGF)." (PMID 40230883, 2025). "Here, we revealed that emodin treatment enhanced anti-tumor effects in an H22 subcutaneous tumor-bearing mice model by increasing CD8+ T cell infiltration and promoting TNF-α, IFN-γ, and Gzms-B secretion." (PMID 40804393, 2025).
tumor (continued). "They secrete significant amounts of pro-inflammatory cytokines and growth factors, such as TNF-α and VEGF, which support tumor cell growth, survival, and angiogenesis by providing essential nutrients and oxygen." (PMID 39895793, 2025). "Tumor cells from the tumor cell line PC9 (HLA-A2+ EGFR mutant NSCLC) were either cocultured with PBMCs in their native state or after stimulation with IFN-γ and TNF-α to increase antigen presentation." (PMID 40459946, 2025). "Elevated cytokine levels, including IL1α, TNFα, IL6, IL10, IL17, and IL12, represent the rejuvenation of tumor immunity in response to combination ICI." (PMID 40313772, 2025). "Functionally, NKp46 expressed on mouse ILC1s interacts with tumor cells through cell–cell contact, increasing ILC1 production of IFN-γ and TNF, and enhancing cytotoxicity." (PMID 39856052, 2025). "The release of pro-inflammatory chemokines and cytokines, such as IL-1, IL-2, IL-6, CCL-2, CCL-8, TNF-α and TGF-β, facilitate the recruitment of brain-resident immune cells to the tumour site." (PMID 41301734, 2025). "It diminishes their capacity to produce key effector cytokines such as IFN-γ and tumor necrosis factor-alpha (TNF-α), crucial for robust anti-tumor immunity." (PMID 40242222, 2025). "This dysfunction is mediated by a pro-inflammatory tumor microenvironment, where cytokines such as IL-1β, IL-6, IFN-γ, and TNF-α activate Toll-like receptors (TLRs), promoting taste bud apoptosis and impairing cellular turnover." (PMID 40868108, 2025). "This aligns with evidence that high APOC1 expression enhances the secretion of cytokines, such as EGF, PDGF, VEGFA, IL-1, IL-8, TNF-α, MMP-9, MMP-2, and NO, which collectively drive tumor cell proliferation, invasion, and angiogenesis." (PMID 39873475, 2025). "The tumor volume of the tumor-bearing mice decreased, and the concentration of multiple molecules in the peripheral blood of the mice, including HIF-1α, TNF-α, VEGF, and MMP-9, was reduced." (PMID 40563539, 2025). "Concurrently, PD-1/PD-L1 blockade reverses T cell exhaustion within the TME, restoring cytotoxic activity, cytokine production, including IFN-γ and tumor necrosis factor-alpha (TNF-α), and tumor cell killing." (PMID 41013723, 2025). "TNF-α also stimulates vascular endothelial growth factor (VEGF) secretion, supporting tumor growth and metastasis, while recruiting MDSCs and regulatory T cells (Tregs) and promoting M2 macrophage polarization." (PMID 41394847, 2025). "Tumor necrosis factor-α(TNFα) and IL-1β are the main inducers of IL-8 expression, and IL-8 can recruit myeloid-derived suppressor cells (MDSC) and reduce the efficacy of tumor immunotherapy." (PMID 40124355, 2025). "Tumor cells overproduce osteolytic factors such as PTHrP, IL-11, IL-6, IL-8, vascular endothelial growth factor (VEGF), tumor necrosis factor (TNF), Jagged 1, and epidermal growth factor (EGF)-like ligands." (PMID 40149349, 2025). "These TILs were associated with the generation of pro-inflammatory cytokines, such as interleukin-2 (IL-2), tumor necrosis factor-α (TNF-α), and interferon-gamma (IFN-γ), suggesting metformin’s effect for activating anti-tumor immune responses." (PMID 40005128, 2025). "CD8+ T cells are the key executors of the anti-tumor immune response and act mainly via the classic perforin/granzyme release pathway and the release of TNF-α and IFN-γ to kill tumor cells and inhibit tumor development." (PMID 40693815, 2025). "Specific cytokines, such as FOXP3, TNF-α, and IFN-γ, regulate tumor immunity, often with elevated expression in CRC." (PMID 40297577, 2025). "In vitro, dHL-60 cells with high LDHA directly promotes the proliferation of pancreatic cancer cells, concurrently reducing TNF-α and IFN-γ expressed by CD8+T cells, thereby amplifying the immunosuppressive and tumor-promoting effects of TANs82." (PMID 39897050, 2025).
tumor (continued). "We confirmed that the 3D growth of tumor cells and the expression of CXCL5 were increased by the conditioned media from IFNγ + TNFα co-treated macrophages, similar to those of IFNγ + LPS stimulation." (PMID 40050422, 2025). "γδ T cells promote apoptosis by cytotoxic substances such as granzymes and perforin, as well as tumor cell (MCF7) senescence via IFN-γ and TNF production." (PMID 40584290, 2025). "The ADCC effect mediates tumor cell death through triggered release of cytotoxic granules (e.g., perforin and granzyme B) and cytokines (e.g., IFN-γ and TNF-α)." (PMID 41293157, 2025). "The transfer of HCC exosome-reprogrammed neutrophils exacerbated tumor progression and induced T-cell exhaustion, as evidenced by the downregulation of IFN-γ and TNF-α, and the upregulation of PD-1 and Tim3 in T cells." (PMID 40083930, 2025). "Another coumarin compound, umbelliprenin, exerts its anti-tumor effect by regulating the immune response through the promotion of pro-inflammatory cytokines such as IFN-γ and TNF-α." (PMID 41142809, 2025). "For instance, activation of caspase-8 by metabolite α-ketoglutarate or TNF-α leads to GSDMC cleavage and subsequent induction of pyroptosis in tumor cells." (PMID 40663398, 2025). "This robust anti-tumor effect correlated with the increase in intratumoral CD40 + DCs and the frequency of granzyme B+/IFN-γ+/TNF-α+ polyfunctional antigen-specific CD8 + T cells." (PMID 40500288, 2025). "We reported a significant, higher than in 4T1 tumor-bearing mice, 2’3’-cGAMP-induced increase in CXCL10, CCL2, CCL4, TNF-α, IFN-α and IFN-β concentrations." (PMID 39857957, 2025). "As already elaborated, tumor-cell-derived CCL3 activates the MAPK pathway, leading to the production of IL-1β, IL-6 and TNF-α." (PMID 41153795, 2025). "TAM-derived cytokines such as IL-6 and TNF-α activate signaling pathways like STAT3 and NF-κB in tumor cells, inducing EMT and increasing metastatic potential." (PMID 41280929, 2025). "The parallel surge of TNF-α and CEA in Stage IV seemingly underscores their link to tumor progression." (PMID 40299527, 2025). "Recent studies have demonstrated that tumor-infiltrating monocytes differentiate into IL-1β-producing TAMs following exposure to prostaglandin E2 (PGE2) and TNF." (PMID 40948749, 2025). "Key cytokines of interest include IL-6, TNF-α, IL-1β (as prototypical pro-tumor inflammatory cytokines), as well as others such as IL-8 (CXCL8), IL-10, and IL-17, which together shape the tumor immune microenvironment." (PMID 41007766, 2025). "TNF-α and NFKB are relevant to several important biological processes, including inflammatory response, immune regulation, tumorigenesis, and tumor cell apoptosis." (PMID 40391219, 2025). "Pro-inflammatory cytokines, including interleukin-6 (IL-6) and tumor necrosis factor-alpha (TNF-α), further contribute to this microenvironment by creating a feedback loop that enhances tumor cell proliferation and survival." (PMID 40227814, 2025). "They directly kill tumor cells by secreting IFN‐γ, TNF‐α, and cytotoxic molecules, while also regulating innate immune responses of cells such as NK cells and macrophages." (PMID 41179703, 2025). "Advanced assays quantify circulating cytokines and chemokines, such as IL-6, TNF-α, and CXCL12, which reflect the immune microenvironment and tumor progression." (PMID 40881677, 2025). "ELISA analysis of the whole tumor microenvironment also demonstrated a reduction in TNF-α, suggesting that tumor-derived IFN-γ can affect the global microenvironment and production of other cytokines within the tumor bed." (PMID 40553564, 2025). "Whether related to chemotherapy or cytokines such as TNF, which independently induce cell death, the last 25 years have produced a myriad of publications that have consistently shown that deletion of NF-κB activity in tumor cells accentuates stress-induced killing." (PMID 40799389, 2025).
tumor (continued). "For instance, in papillary thyroid carcinoma (PTC), the combined stimulation of IFN-γ and TNF-α can significantly synergistically upregulate the expression of CXCL9 and CXCL11, activating the anti-tumor immune pathway." (PMID 41341593, 2025). "IL-6, TNF-α, and CXCL8 are three key pro-inflammatory cytokines extensively involved in remodeling the TME, thereby promoting tumor cell proliferation, metastasis, and immune evasion." (PMID 41376630, 2025). "They play a central role in anti-tumor activity by eliminating tumors through the release of IFN-γ and TNF-α." (PMID 40136347, 2025). "CAR-T Exos increased the number of CD8+ T cells with subsequent elevated levels of TNF-α and IFN-γ in the tumor microenvironment." (PMID 41511353, 2025). "Through the secretion of IFN-γ, TNF-α, and IL-2, these cells enhance CD8+ T cell cytotoxicity, promote Th1 polarization, and facilitate tumor antigen presentation." (PMID 40475782, 2025). "We discovered a striking similarity between the TNF and T cell treatments, with nearly 90% of significantly upregulated phosphorylation sites shared between the two conditions in sensitized TRAF2 KO tumor cells." (PMID 41315176, 2025). "This combination therapy has shown considerable efficacy in remodeling the tumor TME by reducing tumor-infiltrating immune cells such as Tregs and MDSCs while decreasing cytokines like IL-6, TGF-β, and TNF-α." (PMID 40281554, 2025). "However, the same study showed that TNF-α may encourage tumor growth." (PMID 40933989, 2025). "Roseburia intestinalis inhibits tumor growth by inducing cytotoxic granzyme B+, IFN‐γ, and TNF‐α + CD8 + T cells, significantly enhancing the anti‐PD‐1 efficacy in mice carrying MSI low CT26 tumors." (PMID 40530896, 2025). "A decrease in key inflammatory biomarker (such as IL-6, TNF-α, IFN-γ, etc.)levels can reshape the tumor immune microenvironment." (PMID 40429988, 2025). "Inflammatory cytokines such as IL-6 and TNF-α upregulate HIF-1α and KRAS signaling, further enhancing tumor aggressiveness and resistance to therapy." (PMID 40342817, 2025). "This shift in population activates the HMG-B1/NF-κB signaling pathway in macrophages, leading to secretion of the C-C motif chemokine ligand 2 (CCL2) and tumor necrosis factor-α (TNF-α) chemokines, which in turn promotes MDSC infiltration and tumor metastasis." (PMID 40539068, 2025). "Activating receptors, such as NKG2D and NKp46, recognize stress-induced ligands like MICA/B and ULBPs on virus-infected or tumor cells, leading to NK cell activation, cytotoxicity, and cytokine production (e.g., IFN-γ and TNF-α)." (PMID 40498022, 2025). "Cytokines like “tumor necrosis factor (TNF-α), IL-1 beta (IL-1β), and interleukin-6 (IL-6)” are released into the tumor microenvironment by the inflammasome from necrotic cells." (PMID 41068541, 2025). "In vitro, TWEAK amplified TNF-α -mediated cytotoxicity in TNF-α sensitive cells (L929) and auditory cell lines (UB-OC1 and US-VOT-N33) at tumor-secreted concentrations." (PMID 39923035, 2025). "The nebulized NLU showed better anti-tumor, anti-inflammatory, and anti-oxidative effects than oral nintedanib in terms of LDH, CEA, AFP, MDA, TNF-α, and IL-1β." (PMID 41625777, 2025). "The results showed that neutralization with antibodies against TNF-α and IFN-γ significantly reduced the tumor-inhibitory effects of Gl-BSP on S180 and PG tumor cells." (PMID 40035898, 2025). "Mechanistically, APS co-administration enhanced CD8+ T-cell infiltration, increased splenic and thymic indices, modulated cytokine profiles (TNF-α, IL-2, IFN-γ, IL-12, IL-6, IL-10), and reduced PD-1/PD-L1 expression in tumor tissue." (PMID 41487528, 2025). "Tumor necrosis factor alpha (TNF-α) and interleukin-17 (IL-17) are mainly affected by anti-PD-1/anti-PD-L1 therapies because they contribute to the expression of PD-L1 in both tumor and immune cells." (PMID 39936958, 2025).
tumor (continued). "The frequency of PD-1+, CD44hi, Ki67+, TNF+, and IFN-γ+ CD8+ T cells at the tumor were also unchanged in comparing WT versus Fgl2–/– mice." (PMID 40125553, 2025). "Pro-inflammatory cytokines such as interleukin-6 (IL-6) and tumor necrosis factor-alpha (TNF-α) activate signaling pathways like STAT3 and NF-κB, driving tumor proliferation and survival." (PMID 40486628, 2025). "We found that emodin treatment enhanced anti-tumor effects by increasing CD8+ T cells infiltration and promoting TNF-α, IFN-γ, and granzyme B (Gzms-B) secretion." (PMID 40804393, 2025). "Meanwhile, PCR results indicated high expression of TNF and CCL2 in tumor samples, confirming this effect at the genetic level." (PMID 39865310, 2025). "IgE antibodies recruit macrophages through the TNFα/MCP-1 signaling pathway, enhancing the anti-tumor immune response and thereby inhibiting the growth of ovarian cancer." (PMID 41357192, 2025). "Inhibited COX-1 and COX-2 pathway, reduce the production of thromboxane B2 and prostaglandin E2.Inhibited the mRNA and protein expression of TNF-α in RAW264.7 cells to realize its anti-inflammatory and anti-tumor effects." (PMID 41356003, 2025). "When combined with anti-PD-1 therapy, ES@CuO significantly increased tumor-infiltrating lymphocytes and upregulated key cytokines (IL-6, TNF-α, IFN-γ), confirming its ability to reprogram the immunosuppressive tumor microenvironment via cuproptosis." (PMID 40791799, 2025). "Mechanistically, IL-24 enhances anti-tumor immunity by promoting the secretion of pro-inflammatory cytokines e.g., Interferon (IFN-γ), Tumor necrosis factor (TNF-α), activating immune effector cells such as CD8+ T cells and NK cells." (PMID 40806452, 2025). "Regarding their functionality, CD8+ T cells exert their effects on tumor cells through the elevated expression of perforin, granzyme B, IFN-γ, and TNF-α." (PMID 38778609, 2025). "Therefore, a combined intervention targeting the complex regulatory network formed by HMGCR, TNF-α, and Hedgehog signaling pathways may offer novel therapeutic approaches to overcome tumor resistance and metastasis, thereby opening new avenues and strategies for cancer treatment." (PMID 41450917, 2025). "Similar to the previous findings, TPP1 positive macrophages secrete TNF and TGFB1 acting on tumor cells, thereby enhancing the proliferation of tumor cells." (PMID 40620715, 2025). "In vitro coculture experiments have demonstrated that LSECs and metastatic tumor cells interact via ICAM‐1/LFA‐1, promoting the release of tumor‐derived PGE‐2, IL‐6, VEGF, and MMPs, as well as LSEC‐derived IL‐1β, IL‐6, and TNF‐α into the TME." (PMID 40027151, 2025). "Chronic ER stress and UPR activation promote inflammation through pathways like NF-κB and TNF, contributing to HCC development across all tumor stages." (PMID 41012682, 2025). "The coordinated action of TNF-α and IL-1β leads to a sustained CCL2 release from tumor and endothelial cells." (PMID 41341593, 2025). "TNF-α exerts its effects through two receptors, TNFR1 and TNFR2, and its role in the tumor microenvironment is complex and context-dependent." (PMID 40286597, 2025). "M1 macrophages exhibit a strong pro-inflammatory profile, secreting cytokines such as TNF-α, IL-1β, and IL-6, thereby activating additional immune cells, especially CD8+ T cells, and enhancing tumor immune surveillance." (PMID 40475760, 2025). "In hypoxic tumor microenvironments (TME), macrophage-derived TNF-α promotes cancer cell pyroptosis via caspase-8-mediated cleavage of GSDMC." (PMID 40200299, 2025). "The expression levels of pro-inflammatory and tumor-related genes, including VEGF, MMP9, TGF-β, TNF-α, COX-2, PGE2, and IL-6, were significantly downregulated in a dose-dependent manner following treatment with ATD-PLGA NPs compared to the untreated group." (PMID 40808199, 2025).